DHX40P1 (DEAH-box helicase 40 pseudogene 1)
Synonyms: DHX40P
Gene: Transcribed unprocessed pseudogene on chromosome 17 (59,976,009 to 60,002,384, reverse strand). Ensembl gene ENSG00000266992.
Diseases named in the same sentence as DHX40P1 in open-access papers:
DHX40P1 is named in the same sentence as 2 diseases in open-access papers, as found by Europe PMC text mining. Sharing a sentence is not in itself a finding about the gene and the disease.
DHX40P1 shares sentences with these, for which no sentence is quoted: breast carcinoma (1 paper); tumor (1).